NRP2 (neuropilin 2)
Diseases named in the same sentence as NRP2 in open-access papers (continued):
Sharing a sentence is not in itself a finding about the gene and the disease.
tumor (continued). "NRP2 exerts a key role in lymphangiogenesis and lymphovascular invasion and affects the function of epithelial–mesenchymal transformation in the evolution of tumor transmission and metastasis." (PMID 36421685, 2022). "Indeed, NRP2 maintains the tumor-initiating cells by stimulating α6β1 integrin, this interaction inducing the FAK/Ras pathway and thus leading to the activation of GLI1." (PMID 34277411, 2021). "Down-regulation of NRP1 by shRNA in ccRCC cells decreases migration, invasion and experimental human tumor growth, while NRP2 down-regulation results in decreased tumor cell extravasation in the lymphatic network and reduced cell metastatic dissemination in immunodeficient models." (PMID 33461580, 2021). "have described that VEGF/NRP2 signaling is important in tumor initiation." (PMID 34277411, 2021). "Thus, NRP2, expressed during macrophage differentiation, is induced by tumor cells and regulates macrophage phagocytosis." (PMID 34277411, 2021). "However, it was later shown that tumour cells are able to form and maintain blood vessels by expressing neuropilin-2, EphA2, and laminin-15γ2." (PMID 34638234, 2021). "Interestingly, knocking out NRP2 in osteoclasts in a PCa model of bone metastasis significantly inhibited tumor growth." (PMID 33990538, 2021). "Integrin α5 affects tumor cell extravasation by interacting with neuropilin 2 (NRP-2)." (PMID 33916607, 2021). "In addition, α5β1, α6β1, and α9β1 expressed on tumor cells are capable of binding to endothelial cell-expressed NRP-2, thereby facilitating cancer cell binding to the endothelium, followed by promoted tumor cell extravasation in distinct cancer types." (PMID 33916607, 2021). "Neuropilin-1 (NRP-1) and neuropilin-2 (NRP-2) act as co-receptors to members of the VEGF-receptor family and have been shown to play roles in vascular growth in developmental angiogenesis as well as tumor-associated angiogenesis." (PMID 35087885, 2021). "In most cancers, the co-expression of NRP1 and NRP2 stimulates tumor growth and invasiveness." (PMID 32766254, 2020). "NRP2 promoted efferocytosis of apoptotic tumor cell debris by TAMs and facilitated tumor growth." (PMID 32276464, 2020). "A semiquantitative analysis of PlGF, VEGFR-1, NRP-1, and NRP-2 levels in this tumor, performed by immunohistochemistry on tumor specimens from patients undergoing extrapleural pneumonectomy, showed that the four factors were specifically overexpressed in mesothelioma." (PMID 32085654, 2020). "Tumor growth was significantly reduced in anti-NRP2-treated mice compared with PBS-treated mice." (PMID 32983407, 2020). "Interestingly, the tumor-bearing mice treated with the combination of SAM+anti-PD-1 had the lowest expression of Nrp2 compared to other groups." (PMID 32983966, 2020). "Expression of NRP2 is mostly correlated to tumor progression." (PMID 32766254, 2020). "However, its cleaved form, p65-SEMA3C, stimulates tumor lymphangiogenesis and metastatic dissemination of cancer cells expressing NRP2." (PMID 32766254, 2020). "In summary, based on our systematic analyses of NRPs and PLXNs in terms of their expression, association with patient survival, immune subtype, and tumor infiltration, we found that NRP1, NRP2, PLXNA1, PLXNA3, PLXNB3, PLXNC1, PLXND1 were mainly associated with poor prognosis." (PMID 32640719, 2020). "Furthermore, NRP2 promoted efferocytosis of apoptotic tumor cell debris by TAMs and facilitated tumor growth." (PMID 31766495, 2019). "Also, in biliary tract cancer with strong expression of NRP1 and NRP2, Wnt and PI3K signaling are associated with tumor angiogenesis." (PMID 30717262, 2019). "We have previously shown that NRP2 derived effects in macrophages are essential for tumor growth." (PMID 31664117, 2019). "Indeed, several studies have shown that targeting either NRP1 or NRP2 can inhibit tumor initiation and decrease resistance to other therapies." (PMID 30678134, 2019).
tumor (continued). "We expect that the xMAP‐based assay of Nrp1 and Nrp2 could be clinically applied in early‐stage cancer screening, tumor malignancy analysis, and patient prognosis assessment." (PMID 30758083, 2019). "Thereby, M2 macrophages facilitate tumor progression in a NRP2-dependent manner." (PMID 30717262, 2019). "This hypothesis is further strengthened by a study that showed NRP2 expression during macrophage differentiation, which is induced by tumor cells and regulates phagocytosis in macrophages." (PMID 31766495, 2019). "NRP–2 exerts vital functions in lymphatic endothelial cells, neurons, and tumour cells." (PMID 31211440, 2019). "Liposomal complexes of NRP-2-targeted siRNA (NPR-2-siRNA-DOPC) could be used to slow down the tumor growth." (PMID 29861465, 2018). "Importantly, the expression of neuropilin-1 or its homologue neuropilin-2 by cancer cells was related to tumor initiation, growth, metastasis and immunity." (PMID 29547633, 2018). "As shown for some of the semaphorins, these proteins can compete with VEGF due to its interaction with neuropilin receptors (NRP1 and NRP2), which leads to inhibition of endothelial cell migration, proliferation, and capillary structures formation of the tumor." (PMID 30304095, 2018). "This blocks the binding of VEGFC to NRP2 without affecting Semaphorin binding and reduced tumor-associated lymphangiogenesis and metastasis." (PMID 29067024, 2017). "This indicates a potential role of NRP2 in these two neoplasms." (PMID 29067024, 2017). "Nrp2 protein levels remained unchanged in U87-bevS versus U87-bevR tumor lysates." (PMID 28938007, 2017). "Previous work from our lab has documented a role for NRP2 in maintaining high endocytic activity on cancer cells by affecting the maturation of early to late endosomes, thereby favoring oncogenic activity of the tumor cells." (PMID 29067024, 2017). "NRP2 down-regulation in tumor cells significantly influenced the biological activities of its two ligands, semaphorin 3F and VEGF while inducing an increase of VEGF protein levels in conditioned media, resulting in increased paracrine activation of endothelial cells." (PMID 28350837, 2017). "Thus, Rab17 and Vamp8-dependent sequestration of NRP2 within the endosomes of tumour cells is likely to represent a remnant of the transcytotic system that still acts to suppress basement membrane disruption and the DCIS to IDC transition." (PMID 28062852, 2017). "Similarly, NRP2 promotes tumor growth and metastasis in pancreatic adenocarcinoma and colorectal cancer models." (PMID 26030152, 2015). "In this line, NRP2 expression could be used as marker of persistent TGF-β activity in HCC patients which is indicative of HCC progression via the tumor promoting arm of TGF-β." (PMID 26573807, 2015). "Specifically, SEMA3F binding to NRP2 inhibits tumor angiogenesis and metastasis." (PMID 24999452, 2014). "The onset of these tumours was significantly delayed by NRP2 inhibition." (PMID 23436775, 2013). "Moreover, down-regulation of GLI1 or inhibition of NRP2 in SUM1315 NRP2high cells significantly decreased tumour initiation." (PMID 23436775, 2013). "Specifically, targeting NRP2 could be effective in reducing tumour burden and recurrence because it will disrupt an autocrine signalling pathway that is necessary for the function of TICs, in addition to inhibiting lymphangiogenesis as previously suggested." (PMID 23436775, 2013). "Cells derived from TBP tumours form mammospheres that are dependent upon NRP2." (PMID 23436775, 2013). "Our laboratory and others have shown that tumor cell–derived NRP-2 plays a role in tumor growth." (PMID 22028766, 2011).
tumor (continued). "In addition, intraperitoneally treatment of tumor bearing mice with liposomes containing NRP2 siRNA reduces tumor growth and metastasis." (PMID 24212788, 2011). "Moreover, the neutralizing mAb bevacizumab, known to inhibit the proliferation of microvascular endothelial cell line HMEC-1, was used to address the potential role of VEGFA in NRP2-mediated tumor cell growth." (PMID 21747928, 2011). "Particularly, NRP2 knock-down hampered anchorage-independent growth in several tumor models." (PMID 21747928, 2011). "Neutralization of NRP2 in different tumor models led to tumor lymphangiogenesis inhibition." (PMID 21747928, 2011). "Moreover, NRP2 is a functional receptor for semaphorin 3F, which was described as an inhibitor of angiogenesis, tumor progression and metastasis." (PMID 21747928, 2011). "To confirm these results, we decided to investigate if NRP2 targeting using specific siRNA could inhibit tumor formation." (PMID 21747928, 2011). "Intraperitoneal administration of NRP-2 siRNA-DOPC decreased the tumor burden in mice (p = 0.01)." (PMID 22028766, 2011). "Furthermore, mice treated with NRP-2 siRNA-DOPC exhibited a significant reduction in tumor mass compared with tumor mass in mice treated with cntr siRNA-DOPC sequences (160±18 mg vs. 459±102 mg, respectively; p<0.05)." (PMID 22028766, 2011). "However, the function of the NRP-2 on the tumor cell membrane in human cancers, including those of gastrointestinal (GI) neuroendocrine and gastric origin, remains largely undefined." (PMID 22028766, 2011). "Nrp2 expression was identified in both marginal and central areas of the tumor." (PMID 19580679, 2009). "Recently, Nrp2 was shown to play a role in cancer by promoting tumor cell metastasis." (PMID 19580679, 2009). "Neuropilin-2 (NRP-2) expression correlates with advanced tumor stage and grade." (PMID 18549507, 2008). "Moreover, our research found that activation of NRP2 could stimulate phagocytosis in macrophages and orchestrate immunosuppression to facilitate tumor growth." (PMID 39119581, 2024). "Additionally, the SEMA3F/NRP2 pathway may present novel therapeutic avenues if subsequent foundational studies corroborate its purported tumor-suppressive capabilities." (PMID 39232098, 2024). "However, the tumor cell-intrinsic role of Nrp2 in cancer progression is incompletely understood." (PMID 35158941, 2022). "To determine whether cotargeting endothelial NRP1 and NRP2 impedes tumor growth in already established tumors, we next performed intervention CMT19T allograft studies in our NRP1flflNRP2flfl.ECKO animals, delaying tamoxifen administrations until 7 days after cell implantation." (PMID 36970722, 2022). "Notably, NRP1flflNRP2flfl.ECKO tumors also exhibited significantly less vasculature than either NRP1flfl.ECKO or NRP2flfl.ECKO tumors, suggesting that the dual targeting of both NRP1 and NRP2 elicits a compounded antiangiogenic response to inhibit tumor development and growth." (PMID 36970722, 2022). "Likewise, the cell-penetrating peptide iRGD containing the CendR sequence can first target integrin receptor to cross the blood–brain barrier and then provides the second moiety to bind Neuropilin-1 (NRP-1) and Neuropilin-2 (NRP-2) for crossing the brain–tumor barrier." (PMID 36531004, 2022). "Consequently, this work suggests that N2E4 has the potential for targeting therapy of PDAC, contributes to understanding the NRP2 function in cellular movement and tumor metastasis, and lays a foundation for the future development of NRP2-based targeted therapy for PDAC." (PMID 34336654, 2021). "Also, the group with silenced NRP2 in the tumor cells demonstrated increased necrosis." (PMID 33990538, 2021). "In addition to the direct effect on HB cells observed in our study, anti-NRP2 approaches might disrupt the tumor microenvironment." (PMID 34239847, 2021).
tumor (continued). "Similarly, Nrp2, which is also highly expressed in cluster 0, was recently shown to facilitate tumor growth by promoting efferocytosis to allow for clearance of apoptotic tumor cells." (PMID 33072601, 2020). "Furthermore, transcript levels of NRP2, a VEGFR2 co-receptor, were significantly higher in IT samples than in MLP tumor samples, which suggests that NRP2, not VEGFR2, is associated with PNET angiogenesis." (PMID 32983407, 2020). "The expression of NRP2 in M2-macrophages correlates with their ability to carry out efferocytosis, a process in which apoptotic cells, e.g., tumor cells, are engulfed by macrophages without eliciting inflammation and a potential immune response against tumor cell components." (PMID 30717262, 2019). "Similarly, miR-486-5p acts as a tumor suppressor in colorectal carcinoma by downregulating NRP2." (PMID 30717262, 2019). "Furthermore, we measured Nrp1 and Nrp2 in serum samples from 45 tumor patients." (PMID 30758083, 2019). "Furthermore, the function of NRP‐1/NRP‐2 heterodimers should be investigated in PDAC as their similar but unique properties may confer different advantages to the tumor." (PMID 30216699, 2018). "Our demonstration that the α6β1 integrin functions in concert with NRP2 to drive autocrine VEGF signalling is significant because this integrin has been implicated in the function of tumour stem cells and high α6 expression characterizes tumour initiating populations." (PMID 23436775, 2013). "Indeed, NRP2 may regulate tumor progression by several concurrent mechanisms, not only angiogenesis but lymphangiogenesis, epithelial-mesenchymal transition and metastasis." (PMID 24212788, 2011). "The expression of NRP2, the well-known SEMA3G receptor, in tumor areas was confirmed by immunofluorescence analysis." (PMID 40533501, 2025). "For NRP2, a marked increase in mRNA levels was observed in primary SKCM tumour samples compared to normal tissue." (PMID 40134439, 2025). "Tumor-derived VEGFA and TGFβ2 signals were received by NRP2 and TGFβR2/3 receptors present on MES and RG-PC cells, respectively, with PDGFA_PDGFRA signaling from tumor cells directing final PC specification." (PMID 40562749, 2025). "This conclusion is supported by our finding that radiotherapy selects for the survival of tumor cells with high NRP2 surface expression and that inhibiting VEGF/NRP2 sensitizes this population to radiation." (PMID 39352757, 2024). "We report that NRP2-expressing cells serve as a hub for NO production, by enhancing NOS2 transcription via Gli1, which creates local fields within the tumor that can protect the cells from radiation." (PMID 39352757, 2024). "Our results also showed that the expression of NRP1 and NRP2 was positively correlated with the infiltration of CAF, which can interact with tumor cells, promote tumor growth and maintain malignant tendency." (PMID 37190154, 2023). "Our results showed a positive correlation between Treg infiltration levels, and NRP1 and NRP2 expression was observed in PAAD, which partially revealed the immunosuppressive TME and poor prognosis of tumor patients with high expression of NRP1 and NRP2." (PMID 37190154, 2023). "It has been shown that Neuropilin-2 (NRP2), produced by TAMs, stimulates the formation of tumors by controlling the efferocytosis of tumor cells that have died." (PMID 37641132, 2023). "NRP-2, a receptor for VEGF, is also a target of miR-15b and mediates neuronal guidance, angiogenesis, and tumor progression." (PMID 37509289, 2023). "As a transmembrane glycoprotein receptor, NRP consists of two members, NRP-1 and neuropilin-2 (NRP-2), which regulate neurogenesis, angiogenesis, vascular permeability, and immune response, as well as tumor growth and vascularization." (PMID 36903540, 2023).
tumor (continued). "Finally, to exclude tumor size as a statistical confounder, and therefore assess whether the loss of endothelial NRP1 and NRP2 directly influences pathologic angiogenesis, tamoxifen administration was suspended further until 12 days after CMT19T cell implantation." (PMID 36970722, 2022). "According to the RNA-seq analysis, NRP2, NODAL, and NR2F2 were highly expressed, while EGF was lowly expressed in tumour tissue." (PMID 36172369, 2022). "The analysis of tumor tissue by immunohistochemistry showed a high expression of tight junction proteins PARD3, TJP2, and occludin (OCLN) in subcutaneous tumors formed by Nrp2−/− CRC organoids." (PMID 35158941, 2022). "The findings presented in this study demonstrate that tumor angiogenesis and growth can be arrested completely by cotargeting endothelial NRP1 and NRP2." (PMID 36970722, 2022). "Here we demonstrate, using NRP1ECKO, NRP2ECKO, and NRP1/NRP2ECKO mouse models, that maximum inhibition of primary tumor development and angiogenesis is achieved when both endothelial NRP1 and NRP2 are targeted simultaneously." (PMID 36970722, 2022). "In our previous studies, Semaphorin 3 F was revealed to act as a tumor suppressor of ESCC and involved in the lymph node metastasis development by regulating neuropilin 2 (NRP2), which is a direct target of miR-613." (PMID 34516335, 2021). "Analysis of the TCGA database showed that the NRP2 pathway, more than the NRP1 pathway correlates with tumor aggressiveness only in metastatic patients." (PMID 33461580, 2021). "We identified six survival-related genes, EMP1, TPM1, NRP2, FGFR1, CAVIN1, and LATS2, found in the DEG analyses of both, tumor-paracancerous and paracancerous-normal differentially expressed data sets." (PMID 32695477, 2020). "For instance, while SEMA3A binds specifically to NRP1 and SEMA3F binds to NRP2-containing holoreceptors to promote tumor cell normalization and inhibit metastasis in endothelial cells, SEMA3C shows similar affinities for NRP1 and NRP2." (PMID 32640719, 2020). "More importantly, we revealed a potentially significant role of NRP2 in PNET angiogenesis and tumor growth in an in vivo animal model and clinical specimens." (PMID 32983407, 2020). "Therefore, it is tempting to speculate that NRP2 enables macrophages to efferocytose without causing an immune response against apoptotic tumour cell components." (PMID 32708258, 2020). "NRP2 is expressed preferentially on breast CSCs and VEGF/NRP2 signaling was shown to be important for the genesis of TNBCs and tumor initiation." (PMID 30678134, 2019). "In TNBC, for example, a high frequency of tumor cells express both VEGF and NRP2 but only a fraction of these cells has CSC properties." (PMID 30678134, 2019). "An immunoglobulin FC-fused tumor tissue penetrating peptide, Fc-TPP11 (HTPGNSKPTRTPRR), binds to the VEGF-binding site of NRP1 with 1000-fold higher affinity as compared to NRP2." (PMID 30717262, 2019). "Increased expression of NRP2 results in down-regulation of EGFR, slowed tumor growth, and suppression of an EGFR “rescue” pathway of tumor cells, which is turned on as a protective response to MET-directed tumor therapy." (PMID 30717262, 2019). "VEGF/NRP2 in connection with α6β1 facilitates FAK activation, which contributes to tumor de-differentiation and initiation." (PMID 30871059, 2019). "In tumor blood vessels, two key molecules (neuropilin-1, NRP-1, and neuropilin-2, NRP-2) can regulate tumor tissue vasculature permeability and enhance permeability through the interaction between the C-end Rule (CendR) motif and neuropilin." (PMID 31346334, 2019). "To test tumor-inhibitory effects of siRNA-mediated knockdown of GIPC1, NRP1 and NRP2 more rigorously in an in vivo model, we subcutaneously transplanted Colo357 cells into the both flanks of immunocompromised mice." (PMID 31664117, 2019).